MYCN (MYCN proto-oncogene, bHLH transcription factor)
Diseases named in the same sentence as MYCN in open-access papers (continued):
Sharing a sentence is not in itself a finding about the gene and the disease.
neuroblastoma (continued). "In essence, MYC family protein expression retained its prognostic significance in the presence of standard neuroblastoma risk factors in the Cox models for both EFS and OS in High MKI neuroblastomas, and it had a better predictability of adverse outcome than MYCN protein expression alone." (PMID 29464082, 2018). "MYCN amplification is the most prominent genetic alteration in neuroblastoma." (PMID 28817597, 2017). "Moreover, inhibiting MDM2 activity in MYCN-amplified neuroblastoma sensitizes cells to chemotherapy." (PMID 28358317, 2017). "Loss of chromosome 11q, most commonly seen in tumors without MYCN amplification, occurs in approximately 33% of neuroblastomas and is associated with a poor prognosis." (PMID 28055978, 2017). "Using a zebrafish model system that reproduces human MYCN amplified, aggressive neuroblastoma, we could confirm the anti-tumor effect of the combination in an in vivo model." (PMID 28596528, 2017). "Together, this shows that MYCN expression reprograms neuroblastoma metabolism." (PMID 28358317, 2017). "Targeting key enzymes involved in metabolic pathways, such as ornithine decarboxylase (ODC), which catalyzes the rate limiting step on polyamine biosynthesis, and hexokinase (the first step on glycolysis), which not only induces neuroblastoma cell death, but also reduces MYCN protein levels." (PMID 28358317, 2017). "AURKA has also been shown to interact with MYCN in neuroblastoma and may play important roles also in other tumors." (PMID 28358317, 2017). "Finally we showed that the integrin-targeted dual pan- PI3K/BRD4 inhibitor, SF1126, potently blocked tumor growth and tumor angiogenesis along with decreasing MYCN mRNA and protein in subcutaneous neuroblastoma xenografts." (PMID 28881723, 2017). "MYCN is critically involved in neuroblastoma tumor aggressiveness and resistance to therapy." (PMID 28358317, 2017). "Interestingly, while other tissues and tumor type cell lines downregulate MYCN mRNA levels post-transcriptionally, in rhabdomyosarcoma, as in neuroblastoma, MYCN is expressed at both mRNA and protein level." (PMID 28358317, 2017). "We therefore further investigated associations of TGF-β signalling genes and outcome in neuroblastoma tumour data and whether pharmaceutical modulation of the TGF-β pathway can enhance the effectiveness of RA treatment in MYCN-amplified cell lines." (PMID 28187790, 2017). "We thereby identified how MYCN globally modulates the differentiation response and identified network nodes which can be therapeutically targeted to prevent amplified MYCN from inhibiting the RA-induced differentiation of neuroblastoma cells." (PMID 28187790, 2017). "Studies of the TH-MYCN mouse model have shown that MYCN is sufficient to drive neuroblastoma." (PMID 28358317, 2017). "The loop involving MYBL2 and MYCN might constitute a therapeutic target particularly for the 20% of aggressive neuroblastomas where amplification of MYCN is observed." (PMID 28467792, 2017). "MYCN is known to negatively regulate NMYC downstream-regulated gene 1 (NDRG1) in neuroblastomas." (PMID 29018329, 2017). "Taken together, this suggests that the established MYCN amplification pathway may be used as a good-quality biomarker for the discrimination between the MYCN-amplified and wild-type neuroblastomas." (PMID 29137381, 2017). "Our results with 106 primary neuroblastomas reveal that TIAM1 has a higher incidence of variants (11%), and they significantly associate as an independent variable with better outcome, even in the concomitant presence of MYCN amplification or ALK mutation." (PMID 28423360, 2017). "We propose, therefore, that the available PI3K inhibitors, such as the LY294002, Idelalisib and Quercetin, may be used to supplement the current therapies for the MYCN-amplified neuroblastomas." (PMID 29137381, 2017).
neuroblastoma (continued). "Our results here expand these findings to a group of 54 stage 3 neuroblastomas, and show that 68% (mean) of microvessels in the aggressive stage 3 tumors (MYCN amplified/unfavorable histology) expressed integrin αvβ3 compared to only 34% (mean) in the non-MYCN amplified/favorable histology ones." (PMID 28881723, 2017). "Moreover, SF1126 suppressed MYCN expression and MYCN associated transcriptional activity in IMR-32 and CHLA136, resulting in overall decrease in neuroblastoma cell viability." (PMID 28881723, 2017). "However, amplified MYCN prevents neuronal differentiation, and aberrant MYCN signalling alone is sufficient to induce neuroblastoma in animal models." (PMID 28187790, 2017). "We explored differences between cultured tumor cells and primary tumor tissues by comparing the gene expression profiles of MYCN amplified neuroblastoma cell lines with tissue samples from a publically available data set (Mixed Neuroblastoma – Versteeg; R2 database)." (PMID 28837150, 2017). "They observed a ≥2-fold increase in the time to event in treated mice, and speculated that the enhanced MYCN-driven cell cycle progression might help sensitize neuroblastoma cells to agents that block mitotic progression." (PMID 28036269, 2017). "In recent years, several genetic changes, such as MYCN amplification, loss of heterozygosity (LOH) of chromosomes 1p and 11q, and 17q gain, have been identified in neuroblastoma specimens, which have been shown to correlate with its aggressive clinical features." (PMID 29296183, 2017). "Several germline and sporadic mutations predisposing to neuroblastoma development have been identified, including PHOX2B, anaplastic lymphoma kinase (ALK), polypeptide N-acetylgalactosaminyltransferase 14 (GALNT14), and MYCN." (PMID 28358317, 2017). "We next performed a statistical analysis to establish which gene expression profiles and molecular pathway activation strengths may serve as the good quality biomarkers for the discrimination of the MYCN –amplified neuroblastomas." (PMID 29137381, 2017). "Small molecule inhibitors of AURKA, such as MLN8054 and MLN8237 (Alisertib), have been described to reduce MYCN stability by increased degradation, to increase survival in an in vivo model of neuroblastoma, and to reduce neuroblastoma-induced endothelial cell proliferation." (PMID 28358317, 2017). "We therefore suggest that this novel molecular pathway built using purely agnostic high-throughput analytic approaches may be recruited to analyze in depth the molecular consequences of MYCN amplifications in neuroblastoma in further investigations." (PMID 29137381, 2017). "MYCN amplifications and activating ALK mutations or amplifications define, among other molecular aberrations, patient subgroups with highly aggressive and frequently therapy-resistant neuroblastomas." (PMID 29156716, 2017).
neuroblastoma (continued). "The proteomic profiles of MYCN-amplified neuroblastoma cells treated with 10058-F4 or with specific MYCN short-hairpin RNA (shRNA) show similar affected Gene Ontology pathways and processes, where about half of the downregulated genes were previously characterized as MYC target genes." (PMID 28358317, 2017). "The data indicate a significant role of HDAC11 for mitotic cell cycle progression and survival of MYCN-amplified neuroblastoma cells, and suggests that HDAC11 could be a valuable drug target." (PMID 28252645, 2017). "We found that in neuroblastoma cells the MYCN/LSD1 complex binds and represses NDRG1 expression." (PMID 27894074, 2017). "High-risk neuroblastoma disease can be further classified into tumours with or without MYCN amplification that differ substantially in biology and therapy response." (PMID 28192521, 2017). "We aimed to establish MYCN and ALK droplet digital PCR for the routine assessment of copy number status from sequential neuroblastoma blood and bone marrow samples to assist risk stratification and detection of cancer progression via MYCN- or ALK-dependent tumor-promoting subpopulations." (PMID 29156716, 2017). "Despite difficulties in directly targeting MYCN, the bromodomain-mediated inhibition of MYCN attenuated tumor growth and induced apoptosis, conferring a survival advantage in three in vivo models of neuroblastoma." (PMID 28790919, 2017). "However, so far, no integrative large-scale analysis has been published for the gene expression features specific for the MYCN amplification in neuroblastoma." (PMID 29137381, 2017). "These types of variants are not generally detected with commercial amplicon-based NGS panels, despite being of critical importance for the clinical management and diagnosis of paediatric patients (e.g. MYCN amplification in neuroblastoma, EWSR1 in Ewing’s sarcoma)." (PMID 29340109, 2017). "Our data clearly demonstrate that GSK461364 treatment in vivo suppresses growth of xenografts derived from neuroblastoma cells with high-risk characteristics regardless of MYCN status." (PMID 28036269, 2017). "Furthermore, inhibition of glycolysis downregulates MYCN protein levels, leading to neuroblastoma growth arrest and cell death." (PMID 28358317, 2017). "MYCN-amplification is a feature of ∼30% of neuroblastoma tumors and portends a poor prognosis." (PMID 29207623, 2017). "MYCN amplification is central to many advanced stage neuroblastomas which exhibit poor prognosis." (PMID 29018329, 2017). "In addition, specific gene expression signatures were proposed to stratify MYCN-amplified neuroblastoma patients with respect to poor or optimistic prognosis." (PMID 29137381, 2017). "Neuroblastoma (NB) with MYCN amplification is a highly aggressive and metastatic tumor in children." (PMID 27894074, 2017). "Our data also suggest that the phosphoinositide 3-kinase (PI3K) inhibitors may provide new opportunities for the treatment of the MYCN-amplified neuroblastoma subtype." (PMID 29137381, 2017). "Importantly, induction of differentiation in neuroblastoma cell lines with retinoic acid leads to MYCN downregulation, while chemical or genetic downregulation of MYCN leads to neuroblastoma differentiation." (PMID 28358317, 2017). "Interestingly, in tumors with MYC or MYCN overexpression, glycolysis is less important as compared to glutaminolysis in keeping the energy status and for survival, as has been reported in MYCN amplified neuroblastoma cells as well as in MYC-inducible B-cells." (PMID 28430666, 2017). "Significant contributions have been made in the identification of critical drivers of primary tumor formation, such as MYCN amplification and ALK mutations, but few studies have been devoted to the identification of consistent features in neuroblastoma metastasis." (PMID 29137288, 2017).
neuroblastoma (continued). "Regardless, the increase in glutathione led the authors to hypothesize that MYCN-driven neuroblastoma could have an increased dependence upon glutathione metabolism." (PMID 28443280, 2017). "In this study, the relevance of TFAP4 in the context of MYCN-driven neuroblastoma was investigated." (PMID 27448979, 2016). "Encouraged by these results, we examined whether MYCN knockdown affects the miRNA expression levels in neuroblastoma cells." (PMID 27764804, 2016). "In this study, we tested the hypothesis that cisplatin might induce drug resistance in one aggressive MYCN-amplified neuroblastoma by affecting the regulation of endogenous BDNF levels." (PMID 27256407, 2016). "In pediatric cancer, expression of MYCN is selectively confined to tumor tissue in medulloblastoma, neuroblastoma, rhabdomyosarcoma, and a subset of retinoblastoma, four common solid tumors that together account for a substantial proportion of relapsed cancer deaths in children." (PMID 27438153, 2016). "Given the demonstrated inter-regulation between MYCN and microRNAs, we speculated that MYCN and the differentiation-inducing microRNAs might form an interaction network to control the differentiation of neuroblastoma cells." (PMID 27764804, 2016). "The up-regulation of a differentiation-inducing miRNA induced by MYCN could be an important self-defense mechanism against the oncogenic signaling pathways during neuroblastoma tumorigenesis." (PMID 27764804, 2016). "Therefore, MYCN gene amplification and subsequent overexpression represent attractive therapeutic targets for treatment of neuroblastoma." (PMID 27571165, 2016). "To more directly address whether inhibition of protein translation contributes to MCL-1 downregulation following MLN8237 treatment, we first measured the effects of MLN8237 on global protein translation in MYCN-amplified neuroblastoma cells." (PMID 26859456, 2016). "Additionally, in MYCN-amplified neuroblastoma xenograft tumors in mice, cell cycle arrest and a decrease in markers associated with transcription were observed." (PMID 26771642, 2016). "Therefore, in addition to further investigating the role of Wnt activation and examining the effect of Wnt inhibition we profiled MYCN expressing neuroblastoma cells with a range of omic techniques and investigated the status of the Wnt signalling pathway." (PMID 27531891, 2016). "Expression constructs encoding FLAG-tagged wild type or stabilized (CPD-mutated) MYCN proteins were transfected into human neuroblastoma cells lacking endogenous MYCN expression." (PMID 27438153, 2016). "In conclusion, DpC demonstrated a potent cytotoxic profile against neuroblastoma cells with or without MYCN amplification in vitro and was demonstrated to effectively inhibit orthotopic neuroblastoma xenograft growth in vivo without causing marked toxicity." (PMID 27678372, 2016). "However, there was no significant change observed on the expression of these molecules in non-MYCN amplified neuroblastoma cells, suggesting combination specificity to MYCN-amplified neuroblastoma cells targeting NF-kB and mTOR pathways." (PMID 26934655, 2016). "Furthermore, we found that combining MYCN knockdown with overexpression of either miR-506-3p or miR-449a leads to significantly enhanced neuroblastoma cell differentiation comparing to miRNA overexpression alone." (PMID 27764804, 2016). "The MYCN-driven neuroblastomas that arise in these fish express the EGFP that is fused to MYCN, but mCherry is detected only if the tumors arise from a precursor cell that has integrated and expresses the mCherry and GRD transgenes (Figure 7figure supplement 1)." (PMID 27130733, 2016). "There is also evidence that immunosuppressive macrophages (CD206/CD163) induce the cyclo-oxygenase–prostaglandin E2 pathway in aggressive MYCN+ neuroblastoma stromal cells, contributing to proliferation, invasion, angiogenesis, chemotherapy resistance, and immunosuppression." (PMID 28536380, 2016).
neuroblastoma (continued). "SHMT2 has been found to be highly expressed in aggressive MYCN-amplified neuroblastomas." (PMID 26771642, 2016). "Additionally, in MYCN-amplified and MYCN-unamplified/low-expressed human neuroblastoma cell lines cell proliferation decreased significantly, but in MYCN-unamplified/unexpressed cells there was no decrease in cell proliferation." (PMID 26771642, 2016). "We demonstrate that the presence of MYCN amplification in neuroblastoma exhibits synthetic lethality when treated with the BCL-2 targeting agent ABT-199, and that these tumors are further sensitized by the addition of the Aurora A inhibitor, MLN8237, in cell culture models and diverse mouse models." (PMID 26859456, 2016). "Additionally, in a MYCN-amplified neuroblastoma murine model, JQ1 treatment significantly decreased tumor volume and increased survival compared to controls." (PMID 26771642, 2016). "In MYCN-driven neuroblastoma cells, THZ1 led to cell cycle arrest." (PMID 26771642, 2016). "To characterize the relevance of the differential apoptotic response seen in the combined ABT-199/MLN8237 treatment between MYCN-amplified and MYCN-WT neuroblastoma cells, we treated cell lines with each inhibitor alone or in combination and assayed viability after 5 days." (PMID 26859456, 2016). "Therefore, we propose that SGO1 represents a potential molecular target for treatment of MYCN-amplified neuroblastoma." (PMID 27539729, 2016). "Furthermore, TFAP4 and MYCN co-operatively regulate a defined subset of genes to drive cell proliferation and migration in MYCN-driven neuroblastoma cells." (PMID 27448979, 2016). "Additionally, proliferation in MYCN-amplified neuroblastoma cells was decreased with siMYCN treatment." (PMID 26771642, 2016). "In neuroblastoma, the most common extracranial solid tumor of childhood accounting for approximately 15% of all childhood cancer related deaths, amplification of the MYCN oncogene in tumors represents one of the most powerful prognostic markers yet identified for this malignancy." (PMID 27448979, 2016). "Neuroblastoma is a complex heterogeneous disease exhibiting a variety of characteristic patterns of genetic aberrations that correlate with clinical outcome, of which cases with ALK mutation and MYCN amplification are more aggressive in nature." (PMID 27483357, 2016). "In addition, MYCN amplification participates in killing of neuroblastoma cells following glutamine deprivation, and this pathway involves NOXA." (PMID 26859456, 2016). "Unexpectedly but interestingly, despite the observed significant effect of MYCN knockdown on inducing neuroblastoma cell differentiation, we found that MYCN overexpression does not have a dramatic effect on inhibiting the differentiation-inducing function of miR-506-3p and miR-449a." (PMID 27764804, 2016). "The Children’s Oncology Group stratified patients into low-, intermediate-, or high-risk groups based on age at diagnosis, International Neuroblastoma Staging System (INSS) stage, tumor histology, DNA index (ploidy), and MYCN (V-myc myelocytomatosis viral-related oncogene) amplification status." (PMID 27686492, 2016). "Intriguingly, this sensitivity was specific only to neuroblastoma cells with MYCN amplification." (PMID 26859456, 2016). "Similar to ICG-001, iCRT14 reduced the viability of MYCN amplified neuroblastoma cells." (PMID 27531891, 2016). "Furthermore, ectopic MYCN expression in MYCN-WT neuroblastoma cells or in epithelium-derived RPE-1 cells led to a concomitant increase in NOXA at both the protein and RNA levels." (PMID 26859456, 2016). "Deregulation of miRNAs expression in malignant neuroblastomas may be due to several factors, as MYCN amplification, chromosomal deletions, or abnormal epigenetic regulation." (PMID 27829219, 2016).